NECTIN4 (nectin cell adhesion molecule 4)
Diseases named in the same sentence as NECTIN4 in open-access papers (continued):
Sharing a sentence is not in itself a finding about the gene and the disease.
cancer (continued). "However, in IHC staining, nectin-4 showed strong expression in the cancer tissue, whereas there was weak or no staining in the adjacent tissues." (PMID 37568798, 2023). "While a growing number of studies have indicated that Nectin4 may be regarded as a potential target for cancer immunotherapy, no study so far has reported the use of Nectin4-targeted CAR-T cells for clinical therapy of malignant solid tumors." (PMID 36479116, 2022). "Because the proliferation of cancer cells is regulated by multiple factors, NECTIN4 might be one of those factors, but not an only responsible factor." (PMID 33808400, 2021). "However, its therapeutic potential in other cancer types, including GC and NSCLC, remains largely unexplored.Despite the growing therapeutic relevance of Nectin-4–particularly, there remains a lack of clinically validated molecular imaging tools to noninvasively assess Nectin-4 expression." (PMID 40542857, 2025). "Interestingly, several cancer cells do not express SLAM or nectin-4, suggesting the presence of a yet unknown entry factor for CDV-OP." (PMID 36645301, 2023). "We found that bladder epithelial cells expressed lower levels of NECTIN4 than skin keratinocytes, either with or without rosiglitazone pre-treatment, and that both normal cells expressed significantly lower levels than RT112 cancer cells." (PMID 40931013, 2025).
infection (48 papers, 2011 to 2025). The state of being infected such as from the introduction of a foreign agent such as serum, vaccine, antigenic substance or organism. "MeV spread from immune cells to nectin-4-positive epithelia is dependent on cell-cell contact, consistent with the highly cell-associated nature of MeV infection." (PMID 28100610, 2017). "We originally showed that many breast, lung, colon, liver, and pancreatic tumor cell lines expressed Nectin-4 and were susceptible to infection by wtMeV." (PMID 27657109, 2016). "After infection amplification in lymph nodes and primary lymphatic organs, multitudes of infected circulating immune cells deliver cell-associated virus to upper airway epithelia cells that express nectin-4 (11, –, 15)." (PMID 39641619, 2025). "Pre-existing humoral α-RABV immunity collapsed within 3 weeks of recCDV NΔ425-479 infection and was not restored over a 3-month post-recovery period, whereas recCDV Nectin-4-blind caused only a temporary moderate decline in α-RABV nAbs titers that spontaneously resolved within 4 weeks of infection." (PMID 38331906, 2024). "Specifically, SLAM mediates infection in immune cells and facilitates virus spread, while Nectin-4 is responsible for mediating infection in epithelial cells." (PMID 40103005, 2025). "All recCDV Nectin-4-blind and a majority of recCDV NΔ425-479-infected animals survived, whereas ferrets inoculated with unmodified recCDV died within 12 days of infection." (PMID 38331906, 2024). "Previously, vaccine-acquired immunity to influenza virus was shown to be compromised in ferrets after infection with nectin-4-blind CDV." (PMID 38415596, 2024). "For MeV, it has been shown that, if nectin-4 forms a strong binding between nectin-4 homodimers, infection by MeV is strongly reduced." (PMID 35038920, 2022). "Infection of keratinocytes with the nectin-4-blind MV resulted in low numbers of single infected cells." (PMID 33031460, 2020). "The infection is subsequently disseminated from the dermal papillae to nectin-4+ keratinocytes in the basal epidermis." (PMID 33031460, 2020). "Nectin-4 has also been detected in the dog brain, suggesting the infection of neurons by CDV and its neuropathogenicity via Nectin-4." (PMID 31398809, 2019). "In our model system, added infected DC cultures were effective at mediating MV epithelial cell infection in a nectin-4-dependent manner, indicating that motility, formation of transmission structures and receptor usage were retained." (PMID 31231395, 2019). "SLAM/CD150 mediates infection of immune cells and dissemination of the virus, whereas Nectin-4 mediates infection of epithelial cells and is considered to play major role in virus transmission." (PMID 31398809, 2019). "During the late stages of the infection, circulating infected immune cells that reach the respiratory tract and the skin can transmit the infection in cis to epithelial cells expressing nectin-4 on their basolateral side." (PMID 31684034, 2019). "SLAMF1 and nectin-4 are found on separate cells in vivo, immune and epithelial, respectively, contributing to a MeV life cycle that involves infection of both the lymphatic system and various epithelia." (PMID 31366072, 2019). "We clearly demonstrate that PPRV infection upregulates the expression of nectin-4 after 1 hpi, which peaked at 24 hpi in EECs." (PMID 29368634, 2018). "Both receptors play a crucial role in viral pathogenesis, with CD150-mediated infection being critical for entry and dissemination and nectin-4-mediated infection critical for virus transmission." (PMID 28481926, 2017). "In the previous study, we have detected nectin-4 in the dog brain and suggested that infection of neurons via nectin-4 contributes to neuropathogenicity of CDV8." (PMID 28336928, 2017). "Infection of these epithelial cells is facilitated by a separate receptor, nectin-4, a component of the adherens junction." (PMID 28100610, 2017).
infection (continued). "Exposure to nectin-4 blocking antibody was permissive for MV-GFP infection (high mean fluorescence) while the exposure to CD46 blocking antibody (low mean fluorescence) was not." (PMID 28968974, 2017). "Subsequently, SLAMF1 and Nectin-4 independent infections of astrocytes were reported using a neurological strain of CDV containing the red fluorescent protein reporter." (PMID 27657109, 2016). "Infection of the primary airway epithelial cells seems to occur via the basolateral surface (adherens junctions) where Nectin-4 is located, presumably through contact with infected immune cells." (PMID 27657109, 2016). "One laboratory has claimed that Nectin-4 is expressed in the brain and contributes to neuron infections." (PMID 27657109, 2016). "When cells were inoculated with rMV-EGFP-SLAMblind at a multiplicity of infection (moi) of 0.1 or 2, all Nectin-4-expressing cells became fluorescent and developed syncytia, a hallmark of MV infection." (PMID 26317644, 2015). "The cellular distribution and expression of CD150 is consistent with the lymphotropism observed in wild type MV infections in vivo, whereas nectin-4 is used by the virus to leave an organism late in infection via the respiratory epithelium." (PMID 25295727, 2014). "CD150/SLAM is known to be involved in the infection of immune cells by wild-type MV while Nectin-4 has been recently described as essential for host-to-host spread of MV." (PMID 23586034, 2013). "However, CDV's ability to bind to human Nectin-4 and replicate in Vero cells expressing primate SLAM receptors remains concerning for its potential to cause cross-species infection." (PMID 40861112, 2025). "Inoculation of human-induced pluripotent stem cell (hiPSC)-derived neurogenin-2 (Ngn2) neuronal co-cultures, consisting of neurons and astrocytes that both lack MeV receptors CD150 and nectin-4, led to productive infection and replication of both rMeVSSPE-F and rMeVF-N465I." (PMID 38329336, 2024). "The infection then spreads to epithelial tissues when the virus binds to nectin-4." (PMID 35891500, 2022). "In addition, experiments with receptor-blind viruses indicate that usage of nectin-4 by CDV is related to the paracellular infection route." (PMID 35038920, 2022). "Current hypotheses speculate that CDV uses the homologous cellular receptors of measles virus (MeV), SLAM and nectin-4, to initiate the infection process." (PMID 35038920, 2022). "Further work is needed to investigate the use of other receptors such as nectin-4, which might be of importance in the infection of the urinary tract." (PMID 35891483, 2022). "Importance of nectin-4 for infection of airway epithelial cells by canine distemper virus." (PMID 35038920, 2022). "In later stages of infection, CDV would usually cross the blood–brain barrier and reach the CNS, causing neurological symptoms, which might be mediated by nectin-4 or a yet unknown cellular entry receptor in astrocytes." (PMID 32244946, 2020). "The infection spreads laterally and apically to the epidermis in a nectin-4-dependent manner." (PMID 33031460, 2020). "Furthermore, a natural outbreak of CDV in monkeys showed predominance of immune system cell infection but also occasional infection of nectin-4-positive cells in the bronchi and bronchioles." (PMID 29743202, 2018). "Following viral amplification in lymphatic organs, morbilliviruses migrate back into airways via basal-lateral infection of epithelial cells using the adherens junction molecule nectin-4 (also known as PVRL4, poliovirus receptor-related 4), allowing transmission to new susceptible hosts." (PMID 26915013, 2016). "Similarly, infection of epithelial cells by CDV using Nectin-4 is required for clinical disease and release of the virus, but not for immune suppression, which is mediated by interaction with SLAMF1." (PMID 27657109, 2016).
infection (continued). "Most viruses use receptors to enter hosts or spread through their epithelial barriers; however, recent studies suggest that MV targets nectin-4 to emerge in the airways and release into the environment late in infection instead of subsidizing the early stages of infection." (PMID 23193403, 2012). "Lentiviruses infected activated CD4+ and CD8+ T cells at the same Multiplicity of infection (MOI), and CD4+ T cells were more likely to express NECTIN-4 TAC and NECTIN-4 TAC28." (PMID 39735536, 2024). "Possible explanations for preferential infection of SLAM+ cells are a better accessibility and affinity of the SLAM receptor compared to nectin-4, which is hidden in the tight junctions of the bronchial epithelium." (PMID 37112814, 2023). "When the cell-to-cell junctions have been interrupted via a scratch or EGTA treatment, the V domain of nectin-4 monomers becomes exposed, allowing CDV to attach to the receptor and successfully initiate the infection." (PMID 35038920, 2022). "At the early stage of infection, the interaction between the PPRV H protein and nectin cell adhesion molecule 4 (NECTIN4) inhibits the activity of the AKT-MTOR pathway and triggers autophagy." (PMID 35402295, 2022). "Two cellular receptors, the SLAM/CD150, and nectin cell adhesion molecule 4 (nectin-4/PVRL4), involved in the entry of morbillivirus in the cell, and subsequent infection, have been identified for both the vaccine and wild-type CDV strains." (PMID 32244946, 2020). "Given the complex bitropic life cycle of morbilliviruses in SLAMF1-positive immune cells and nectin-4 positive epithelia, the role of restriction factors, including BST2, in the innate response to infection is an area of increasing interest." (PMID 31366072, 2019). "Since cattle and SAC showed a similar pathogenesis for PPRV-infection than ferrets infected with a SLAM-blind virus, infection of epithelial cells in the respiratory tract via nectin-4 appears reasonable." (PMID 31817946, 2019). "(Both PVRL4 (Nectin 4) and the CD150/SLAM positive control yielded infections that were characterized by syncytia formation with typical MV cytopathology." (PMID 21901103, 2011). "In rare cases, MeV spreads to the central nervous system (CNS), despite the lack of CD150 and nectin-4 expression, leading to neurological complications that can occur acutely, weeks to months or only years after initial MeV infection." (PMID 38329336, 2024). "Evidence for in vivo usage of CD46, i.e., infection of CD150-/nectin-4- cells, was not obtained during these studies even though there are enormous numbers of CD46-positive cells in close proximity to MV-infected centers." (PMID 29263877, 2017). "Nectin-4 is an adherens junction protein, originally described as poliovirus-receptor-like-4 (PVRL-4), and plays an important role in MV pathogenesis by ‘shedding’ the virus in epithelial airways through the course of infection." (PMID 27782084, 2016). "The recently identified measles receptor on epithelial cells, nectin 4, has a polarized surface distribution enabling infection via the basolateral side but not via the apical plasma membrane." (PMID 24548739, 2014). "Hence, we hypothesize that canine nectin-4 forms more closed types of cis- and trans-homodimers in primary canine airway epithelial cells, which block the access of CDV and thus prevent infection of primary cells from the basolateral side." (PMID 35038920, 2022). "Thus, the epithelial receptor-joined virus is rendered incapable of spreading from the respiratory route, suggesting that nectin-4 plays an essential role in virus egress late in the infection rather than during its initial stages." (PMID 30845967, 2019). "A parallel could be done with studies of CNS invasion with the closely related CDV conducted in dog and showing that astrocytes are neither expressing SLAM nor nectin-4, but remains permissive to the infection." (PMID 31684034, 2019).
infection (continued). "Our infection experiment of H358 cells with CDV-A75/17red revealed that few passages were required for adaptation of this virus to human target cells, while the location of the detected mutations outside of H and F clearly indicated that there is no need for adaptation of H to human nectin-4." (PMID 23554862, 2013). "Since neurons, which are important cell targets affected in SSPE, express neither SLAM nor nectin-4, CDV is thought to exploit a different infection mechanism that does not involve these two receptors." (PMID 35891500, 2022). "The results obtained with ferret ALI cultures were similar to those determined for canine ALI cultures, i.e., infection was detectable only with parental virus and SLAM-blind virus but not with nectin-4-blind virus." (PMID 35038920, 2022). "Our findings revealed that the level of nectin-4 was significantly increased following PPRV infection in EECs but not in FFCs, indicating that PPRV entry and infection plays an important role in regulating the expression of nectin-4 in host epithelial cells." (PMID 29497407, 2018).
adenocarcinoma (13 papers, 2011 to 2025). A common cancer characterized by the presence of malignant glandular cells. "Nectin-4 is typically overexpressed on the surface of adenocarcinoma cells, and is utilized by both laboratory/vaccine and wild-type strains MV14." (PMID 31043633, 2019). "Flow cytometry confirmed that Nectin-4 was expressed on the surfaces of permissive adenocarcinoma cell lines." (PMID 27657109, 2016). "Nectin-2 and nectin-4 were also expressed in the membranes and cytoplasm of the adenocarcinoma cells, although the degree of expression was usually weak." (PMID 25690753, 2015). "Future studies should also explore whether such combinations would also be effective against other Nectin-4-positive adenocarcinomas." (PMID 33406633, 2021). "Similarly, measles virus-derived OVs use nectin-4 (PVRL4), which is overexpressed in several adenocarcinomas." (PMID 41440025, 2025).
colon (2 papers, 2022 to 2024). "Although little is known about the relationship between NECTIN4 and cell cycle, it was reported that inhibition of NECTIN4 resulted in the increase of sub-G1 cell in 5-FU treated colon cancer cells." (PMID 35256687, 2022).
NECTIN4 also shares sentences with these, for which no sentence is quoted: gallbladder carcinoma (3 papers); benign tumors (2); breast adenocarcinoma (2); cholangiocarcinoma (2); gall bladder cancer (2); glioblastoma (2); influenza (2); invasive breast carcinoma (2); ovarian adenocarcinoma (2); penile cancer (2); Pruritus (2); small cell lung carcinoma (2); B cell lymphoma (1); Blindness (1); cognitive decline (1); colon adenocarcinoma (1); COVID-19 (1); dementia (1); Dry skin (1); esophageal tumors (1); extramammary Paget disease (1); gynecological diseases (1); hematological malignancy (1); Hyperglycemia (1); hyperlipidemia (1); hypothyroidism (1); invasive lobular carcinomas (1); laryngeal tumor (1); leiomyosarcoma (1); liposarcoma (1).
A further 22 diseases each share a sentence with NECTIN4 in 1 paper.